HIF1A (hypoxia inducible factor 1 subunit alpha)
Diseases named in the same sentence as HIF1A in open-access papers (continued):
Sharing a sentence is not in itself a finding about the gene and the disease.
tumor (continued). "Hypoxia-inducible factor-1α (HIF-1α) plays an essential role in the adaptive response of cells to hypoxia and is associated with aggressive tumor behavior." (PMID 24765145, 2014). "Hypoxia-inducible factor 1α (HIF-1α), a ubiquitously expressed transcriptional regulator involved in induction of numerous genes associated with angiogenesis and tumor growth, is highly increased by HPV E6." (PMID 24810689, 2014). "Its subunit (HIF-1α) over-expressed in HCC was significantly associated with tumor angiogenesis, invasion and metastasis and poor prognosis." (PMID 24586606, 2014). "Depending on cell type, Wnt/β-catenin signaling also enhances hypoxia-induced EMT by increasing the EMT-associated activity of HIF-1α and preventing tumor cell death." (PMID 25566498, 2014). "MDSCs in turn express and secrete S100A9 and can, under hypoxia, differentiate via HIF-1α dependent transcription into tumor- associated macrophages which secrete angiogenic factors such as VEGF, FGF, TNF-α, and TGF-β." (PMID 25193858, 2014). "AMPK has been linked to the regulation of tumorigenesis and HIF-1α mediates the growth advantage of tumours with reduced AMPK signaling." (PMID 25491408, 2014). "HIF1α can also be activated by nitric oxide, cytokines, insulin growth factors, expression of oncogenes, or mutation to tumor suppressors." (PMID 24489651, 2014). "HIF1α is a key transcription factor that is induced by hypoxia, and it activates the transcription of genes implicated in tumor angiogenesis, cell survival, and resistance to chemotherapeutic drugs." (PMID 25096400, 2014). "Reduction in tumor volume was associated not only with promotion of tumor apoptosis but also with suppression of the pro-angiogenic molecules HIF1α, VEGFα, IL-8 and TGFβ1 and with inhibition of tumor angiogenesis." (PMID 25275595, 2014). "Our model suggests an intriguing possibility that tumor-associated macrophages, specifically through HIF-1α activity, can augment tumor intracellular GSH to help tumor cells develop a resistance to therapy." (PMID 25295611, 2014). "HIF-1α can also be activated under normoxic conditions by growth factors, oncogenic mutation or inactivation of tumor suppressors." (PMID 25166596, 2014). "The hypoxia-inducible factor 1α (HIF1-α, encoded by HIF1A), the primary target of this complex, regulates over 80 genes associated with tumor progression, glycolysis, angiogenesis, and metastasis and is negatively regulated by the VHL elongin BC complex." (PMID 25298778, 2014). "HIF-1α is upregulated in a wide range of solid tumors in humans, and over-expression of HIF-1α is associated with tumor aggressiveness and poor prognosis." (PMID 24980293, 2014). "This is connected with hypoxia close to the irradiated tumor tissue, which causes the upregulation of HIF-1α in hGLUT5-positive microglias." (PMID 24676944, 2014). "In this study, we showed that both HIF-1α and CypA expression were significantly associated with lymph node metastasis and tumor stage." (PMID 24662981, 2014). "Previous studies have shown that the overexpression of HIF-1α is significantly associated with cell proliferation, increased tumor susceptibility, tumor size, lymph node metastasis and prognosis." (PMID 25496056, 2014). "Recent studies have reported that the overexpression of HIF-1α is significantly associated with cell proliferation, tumor susceptibility, tumor size, lymph node metastasis and prognosis." (PMID 25496056, 2014). "HIF-1α has been known to be closely associated with tumor growth and metastasis and the reduction of HIF-1α would directly lead to reduced tumorigenesis and decrease of metastasis." (PMID 25053986, 2014). "Despite, the heterogenous distribution of vascularity, our observation of positive association between HIF-1α and tumor vascularity suggests the HIF-1α induced angiogenesis." (PMID 24165149, 2013). "Activation of a HIF1α transcriptional signature has been reported in tumor-associated macrophages, even under normoxic conditions." (PMID 24324467, 2013).
tumor (continued). "Oxygen regulated transcription factor HIF-1α and the serine/threonine kinase Akt are both essential for development and implicated in tumor growth." (PMID 23590596, 2013). "PX-478, an inhibitor of the hypoxia-inducible factor-1α (HIF1α), has potent antitumor activity against various human tumor xenografts associated with the levels of the HIF1α." (PMID 24119370, 2013). "The protein encoded by the VHL gene is a tumor-suppressor and part of an E3 ubiquitin ligase complex that targets the hypoxia-inducible factor 1α (HIF-1α) for ubiquitination and proteasomal degradation." (PMID 24086736, 2013). "Vice versa, HIF-1α “loss-of-function” results in inhibition of tumor growth in experimental xenograft studies with varying degree." (PMID 24403227, 2013). "Overexpression of HIF-1α has been reported to be associated with a poor prognosis in a variety of malignant tumours." (PMID 23599780, 2013). "The knockdown of prolyl hyroxylase 2 (Phd2), a molecular oxygen sensor and negative regulator of HIF-1α, in human colon cancer increases the number of CD11b+ tumor-associated myeloid cells and promotes angiogenesis." (PMID 24314323, 2013). "The loss of HIF-1α in myeloid cells reversed the hypoxia-induced suppression of T-cell activation resulting in tumor progression." (PMID 23673510, 2013). "Higher levels of HIF-1α in tumours are associated with a poorer prognosis and up-regulation of markers of epithelial mesenchymal transition (EMT) due to HIF-1α actions." (PMID 23638097, 2013). "Though we evaluated comprehensively the association between HIF-1α and tumor outcome, several limitations of this meta-analysis also should also be acknowledged." (PMID 23799043, 2013). "Studies have shown that activation of the HIF-linked molecular cascade leads to tumor aggressiveness by triggering anaerobic metabolism, while pyruvate increases the amount and activity of HIF1α by interference with proteasomal degradation mechanisms." (PMID 24086384, 2013). "The knockdown of HIF-1α or DC101 treatment inhibited tumor growth; however, the combination of HIF-1α knockdown and DC101 caused the greatest degree of growth inhibition." (PMID 22684860, 2013). "Other studies also revealed significant associations between tumor expression of HIF-1α as well as SVV in tumor tissue and pT." (PMID 24086736, 2013). "Among the LSCC samples, HIF-1α expression was closely associated with the clinical stage and level of lymphatic invasion of the tumor cells (P<0.05)." (PMID 23946810, 2013). "Our results showed decreased levels of survivin and MYC, genes associated with tumor progression, and HIF1A and VEGFR2m, that are associated with tumor progression and angiogenesis in the cabozantinib–treated C4-2B tumors." (PMID 24205338, 2013). "Clinicopathological analysis showed that both LOX and HIF-1α expression are significantly associated with tumor FIGO classification (p=0.035 and p=0.032), tumor size (p=0.033 and p=0.032) and lymph node metastasis (p=0.016 and p=0.028, respectively)." (PMID 23545606, 2013). "HIF1α overexpression has been associated with increased patient mortality rates in several cancers, while inhibited expression reduced tumor growth in an in vitro study." (PMID 23718763, 2013). "It seems then possible that HIF1α destabilization in oncocytic cells should occur after the homoplasmic shift of the mtDNA mutation and before neovascularization in tumor progression." (PMID 22299657, 2012). "Together, our data supports the association of LCN2 expression and aggressive tumour growth by stimulating angiogenesis through the upregulation of HIF1A and VEGF." (PMID 23056397, 2012).
tumor (continued). "The loss of HIF-1α in endothelial cells reduces metastasis in mouse tumor models, and reduces tumor cell migration through an endothelial layer under hypoxia." (PMID 22264788, 2012). "We found that nicotine promoted the expression of HIF-1α protein, leading to an activation of downstream hypoxia-responsive genes associated with tumor cell proliferation." (PMID 22952803, 2012). "CD24, a cancer stem cell-associated membrane protein, is an effector of HIF-1α-driven primary tumor growth and metastasis." (PMID 23241400, 2012). "Hif1α is also constitutively expressed in tumor cells, where it is associated with resistance to ionizing radiation." (PMID 22016813, 2011). "HIF-1α protein levels are also increased in normoxic cancer cells with loss of function of certain tumor suppressors, most notably VHL in the clear cell type of renal cell carcinoma." (PMID 21709315, 2011). "Response to hypoxia is mediated by the hypoxia-inducible factor 1α (HIF-1α), which is known to regulate the functions of some tumor-associated proteins, such as vascular endothelial growth factor (VEGF), transferrin, and DEC1." (PMID 21829689, 2011). "HIF-1α positivity rate was associated with tumor diameter, because they were usually single, enveloped, and well-differentiated, and there were more diplonts and less heteromorphism when tumors were small." (PMID 22224081, 2011). "It is essential for angiogenesis and is associated with tumor progression and overexpression of HIF-1α has been demonstrated in many common human cancers." (PMID 21819554, 2011). "We have previously demonstrated that reintroduction of wild type FH into a FH deficient tumor cell line results in a marked reduction in nuclear HIF-1α levels." (PMID 21695080, 2011). "TPZ caused a reduction in HIF-1α-positive staining but induced an apparent increase in p-eIF2α-positive staining in tumor tissues of animals, which were consistent with our in vitro studies." (PMID 21085474, 2010). "HIF-1α is commonly expressed in tumors, though the role that HIF-1α deficiency plays in tumor growth is not fully understood." (PMID 20515450, 2010). "Associated with this growth inhibition was a decreased tumor tissue level of VEGF (i.e. a down stream target of HIF1α) (p < 0.05)." (PMID 20470445, 2010). "Hypoxia inducible factor 1α (HIF-1α) plays an essential role in the adaptive response of cells to hypoxia and is associated with aggressive tumour behaviour." (PMID 20565904, 2010). "Statistically significant association was found between tumour grade and total HIF-1α (P = 0.048) or HIF-1αTAG (P = 0.048)." (PMID 20624301, 2010). "More importantly, HIF-1α induction by hypoxia has been associated with the emergence of a more aggressive tumor phenotype." (PMID 20398289, 2010). "Overexpression of HIF-1α promotes tumor growth, whereas the loss of HIF-1α activity dramatically decreases tumor growth, vascularization and energy metabolism." (PMID 21050481, 2010). "The objective of this study was to investigate and compare the tightly controlled level of HIF-1α protein in normal and tumor cells by imaging the dynamic response of different fusion variants of the HIF-1α gene linked to the Firefly luciferase (FLuc) gene." (PMID 19347037, 2009). "Similar to HIF-1α mRNA, the tumor HIF-1α protein expression level was significantly associated with tumor vascular invasion (P = 0.027) and BCLC stages (P = 0.039)." (PMID 19948069, 2009). "The observation in this study of a positive association of HIF-1α with high tumour grade and relapse-free survival supports a similarly upregulated hypoxic response in BRCA1/basal like cancers." (PMID 19724277, 2009).
tumor (continued). "In clinically derived HNSCC samples, CYGB mRNA expression showed a striking correlation with tumour hypoxia (measured by HIF1A mRNA expression P=0.013) and consistent associations with histopathological measures of tumour aggression." (PMID 19568272, 2009). "Increased succinate or fumarate levels as a consequence of SDH and FH deficiency inhibit hypoxia inducible factor-1α (HIF-1α) prolyl hydroxylases leading to sustained HIF-1α expression in tumours." (PMID 19778456, 2009). "In multivariate analysis, logistic regression confirmed a significant association between HIF-1α expression and tumor stage." (PMID 20003271, 2009). "We show that angiogenesis is significantly increased early in this sequence, confirming this recent data, although the greatest increase occurs with tumour invasion, with associated increases in HIF-1α, VEGF and TF expression." (PMID 19623180, 2009). "A high level of HIF-1α is associated with pro-survival of the cancer cell, increased tumor angiogenesis, invasiveness, and resistance to conventional treatments." (PMID 19714248, 2009). "BRCA1 tumours with HIF-1α expression was associated with a shorter relapse-free (P=0.049) but not overall survival (P=0.764)." (PMID 19724277, 2009). "HIF-1α expression has been noted in many different tumor types and has been variably associated with adverse prognosis." (PMID 19014607, 2008). "The cause-and-effect relationship between tumor hypoxia, HIF-1α, CAIX and clinical outcome remains unsettled." (PMID 19578493, 2008). "Because VEGF is under the control of the transcription factor HIF-1α, which is induced by tumour hypoxia, we performed western blot experiments using BxPc-3 cells grown under normoxic and hypoxic conditions." (PMID 18665180, 2008). "We have previously shown that HIF-1α is involved in gastric carcinogenesis and invasive edge tumour expression is associated with an adverse prognosis." (PMID 18283323, 2008). "HIF-1α expression has been noted in many tumours and it has been variably associated with adverse prognosis." (PMID 19014607, 2008). "We found that focally positive HIF-1α expression was associated with a less aggressive tumour phenotype and an improved prognosis." (PMID 17179985, 2007). "Many tumor models have demonstrated a close correlation between local oxygen deficiency and the production of HIF-1α and VEGF." (PMID 17263869, 2007). "It was interesting to note that macrophages and endothelial cells associated with tumour cells within the subserosal tissue also showed strong staining for HIF-1α." (PMID 17179985, 2007). "HIF-1α-expressing tumours were also associated with a significantly shorter disease-free survival (P = 0.04, HR = 1.60, 95% CI = 1.02–2.42)." (PMID 18096060, 2007). "Only a small minority of SCC revealed necrotic tumour areas, frequently associated with HIF-1α expression and expression of CAIX and Glut-1, pointing to a hypoxia induced event." (PMID 16035955, 2005). "The significant relation between tumor grade and stromal HIF-1α overexpression underlines its importance, with all malignant tumors showing HIF-1α overexpression." (PMID 16168127, 2005). "HIF-1α expression was usually diffuse and tended to be more prominent towards the centre of tumour fields, sometimes associated with a better differentiation, indicated by the presence of keratinized tumour parts." (PMID 16035955, 2005). "EGF treatment of tumour cell lines induces HIF-1α expression and constitutively active mutations of EGFR potentiate hypoxic induction of other targets of HIF-1α such as VEGF." (PMID 15365565, 2004). "We have further shown that DEC1 expression is strongly associated with HIF-1α, the hypoxically induced protein angiogenin and tumour grade, suggesting a role for DEC1 in blocking tumour differentiation and potentially apoptosis." (PMID 15328513, 2004).
tumor (continued). "In many human tumours, a close spatial correlation of local oxygen deficiency (determined by assessment of intrinsic or extrinsic hypoxia markers, eg, HIF-1α or EF5) and the production of VEGF was found." (PMID 15305198, 2004). "Additionally, our GSEA results revealed an enhanced inflammatory response signature, marked by increased expression of genes associated with Wnt signalling (ICAM1, HIF1A), a known master regulator of inflammation, tumour progression, and metastasis." (PMID 41486154, 2026). "Hypoxia and HIF-1α are known to be linked to mTOR signaling, so this observed signaling dichotomy may be coordinated by hypoxia and is indicative of multiple tumor cell states." (PMID 41568176, 2026). "Furthermore, HIF-1α-induced STAT3 activity enhances the immunosuppressive functions of tumor-associated macrophages (TAMs) and Tregs, contributing to immune evasion." (PMID 39981236, 2025). "In addition, hypoxia-induced stabilization of HIF-1α drives the reprogramming of tumor-associated macrophages toward an immunosuppressive M2-like phenotype, thereby further promoting immune evasion and tumor progression." (PMID 41142435, 2025). "Thus, HAF causes a switch between HIF1α-dependent to HIF2α-dependent hypoxic responses in cancer cells, promoting stem cancer cell characteristics and more aggressive tumor growth and invasion under prolonged hypoxia." (PMID 39942749, 2025). "Beyond Treg cells, hypoxia-associated HIF-1α activation also promotes immunosuppressive phenotypes in tumor-resident γδ T cells and TAMs, highlighting a broad effect of hypoxia in limiting anti-tumor immunity." (PMID 40468052, 2025). "Likewise, tumor-associated metabolites such as kynurenine, lactate, and adenosine maintain Treg function through activation of AhR and HIF-1α signaling." (PMID 41394821, 2025). "However, in those experiments, the tumor-suppressive antioxidant effect was linked to reduced hypoxia-inducible factor 1-alpha (HIF1α) levels, mediated by prolyl hydroxylase 2 (PHD2) and the von Hippel-Lindau (VHL) ubiquitin ligase." (PMID 40646353, 2025). "Additionally, tumor-associated lncRNAs can modulate the activity of HIF-1α, ultimately exerting either pro- or anti-tumorigenic effects on tumor cells." (PMID 40861273, 2025). "Additionally, HIF-1α expression has been detected in certain stromal cells, ECs, and tumor-associated macrophages (TAMs)." (PMID 40443737, 2025). "Moreover, recent research indicates that HIF-1α expression in tumor-associated macrophages serves as an independent prognostic factor in kidney cancer." (PMID 39757165, 2025). "Furthermore, the association of 18F-FMISO uptake with the glioma tumor grade, hypoxia biomarkers (CA-IX and HIF-1α), and angiogenesis markers (VEGF) has also been reported." (PMID 40283896, 2025). "However, these angiogenesis inhibitors can cause extensive vascular collapse, leading to tumor hypoxia, which activates HIF1α, triggering glycolysis and lactate secretion in hypoxic regions of the tumor." (PMID 40057816, 2025). "In ESCC, HIF-1α expression is implicated in tumor growth, invasion, and metastasis." (PMID 40746896, 2025). "However, a significant association was observed between KRAS G12C mutations and HIF-1α expression in the tumor microenvironment, emphasizing the role of the tumor microenvironment in modulating disease progression." (PMID 39996842, 2025). "Additionally, loss of TET1 enhances tumor adaptive metabolism by upregulating hypoxia-inducible factor 1-alpha (HIF-1α) signaling." (PMID 41394878, 2025). "KRAS, in turn, leads to the activation of HIF-1a through the mitogen pathways activated by protein kinase or phosphatidylinositol 3 kinase, leading to cell division, metastatic behavior, drug resistance, and tumor recurrence, associated with poor prognosis." (PMID 40149887, 2025).